TLR2 (toll like receptor 2)
Diseases named in the same sentence as TLR2 in open-access papers (continued):
Sharing a sentence is not in itself a finding about the gene and the disease.
infection (continued). "Blocking of TLR2 (p = 0.0063) or TLR4 (p = 0.0047) prior to infection or stimulation with 19 kDa significantly increased epithelial pCREB production (p = 0.0163)." (PMID 24489729, 2014). "Cleavage of procaspase-1 to caspase-1 requires TLR2, as TLR2−/− mouse macrophages showed little caspase-1 24 h after infection with LVS." (PMID 24600590, 2014). "Antibody blocking of TLR2 or TLR4 before infection decreased epithelial IL-6 secretion (p = 0.0011 and p = 0.0047 respectively)." (PMID 24489729, 2014). "DAMPs released during infection are detected through TLR2 by immune cells recruited to the ischemic tissue and/or by cells of the ischemic tissue itself, amplifying the inflammatory response and inducing injury upon reperfusion." (PMID 24302927, 2013). "Here, we report that infection of macrophages with F. tularensis triggers the phosphorylation of mTOR downstream effector molecules, and that signaling via TLR2 is necessary for these events." (PMID 24312679, 2013). "Although TLR-2-/- BMM increased H-ferritin in response to infection, this effect was markedly reduced in comparison with WT BMM." (PMID 24349383, 2013). "Our data indicate that in vivo TLR2-mediated recognition significantly contributes to the severe outcome following infection with a highly virulent S. suis ST1 strain." (PMID 23724118, 2013). "But at 6 weeks after infection, the level of PD-L2 on CD11c+ cells from TLR2−/− mice was significantly lower than that of B6 mice." (PMID 24376539, 2013). "Compared to wild-type mice, resistance to primary infection and to re-challenge was similar in TLR9-deficient or TLR6-deficient mice; it was greatly increased in TLR2-deficient mice but impaired in TLR3- or TLR4-deficient mice." (PMID 23853597, 2013). "Toll like receptor 2 (TLR2) is a critical component in the host innate immune response to infections." (PMID 27234389, 2013). "TLR4 signaling drives IEC proliferation during infection, while TLR2 signaling promotes IEC integrity." (PMID 23950714, 2013). "TLR2 signaling has been proposed to be involved in the pathogen recognition process during the infection of Streptococuus, mycoplasma, chlamydia, virus, which are the common pathogens that cause exacerbations and pneumonia in COPD." (PMID 27234389, 2013). "Having observed that lethal IOE infection differentially modulates tlr2 and nod2 levels, we decided to elucidate the contributions of TLR2 and Nod2 to the pathogenesis of fatal ehrlichiosis." (PMID 23526993, 2013). "A possible cooperative role of both receptors during infection has been suggested in a study that evaluated the resistance to infection of TLR2/TLR9-double knockout (TLR2/TLR9−/−) mice." (PMID 23650544, 2013). "According to our previous data, a crucial role of TLR9 was evidenced in the establishment of Th1 response, whereas TLR2 appeared to act as immunoregulator in the early stage of infection." (PMID 23650544, 2013). "Upon infecting these mice along with WT and Sigirr −/− mice, and Tlr2 −/− and Tlr4 −/− mice, all mouse strains were found to survive the infection." (PMID 23950714, 2013). "Infection of pigs with PRRSV tended to up-regulate the mRNA expression of TLR2, 3, 4, 7, and 8 in at least one of the lymphoid tissues and PAMs." (PMID 23631691, 2013). "The infection-induced mobilization was dependent on the presence of toll-like receptor 2 (TLR2), the receptor primarily mediating the invasion of P. gingivalis into host cells, seemingly a prerequisite for exerting its biological effects." (PMID 23355901, 2013). "After infection, TLR2 on monocytes/phagocytes increase already at initial presentation of clinical symptoms, showed a constant high expression on monocytes in the course of neonatal sepsis, and were down-regulated after successful treatment." (PMID 23431318, 2013). "Results clearly showed a TLR2-dependent or -independent innate immune response depending on the strain responsible for the infection, suggesting different mechanisms of cell activation." (PMID 23724118, 2013).
infection (continued). "The different functions of TLR2 and TLR9 observed explain the impact of their deficiency on the resistance to infection." (PMID 23650544, 2013). "Here, we observed that TLR2 expression increased gradually on CD11c+ cells with the infection progression in S. japonicum infected B6 mice." (PMID 24376539, 2013). "In vivo infection with S. aureus caused significantly elevated production of TNF-α and IL-6 in the livers and blood of TLR2-deficient mice compared with those in WT mice, while the hepatic and serum levels of IL-10 decreased in these mice." (PMID 24058538, 2013). "Disease severity correlates to greater TLR4 protein expression on splenic lymphocytes in male mice 3 days after infection while resistance in females correlates to preferential TLR2 expression, especially in spleen lymphocytes." (PMID 23241283, 2012). "The authors found an earlier but transient induction of this cell population by the administration of the combination of TLR9 plus TLR2 agonist concomitantly with the infection." (PMID 21869919, 2012). "Similar to this finding, infection of THP-1 macrophages with a recombinant M.smegmatis strain expressing PPE18 led to TLR2 dependent induction of IL-10." (PMID 23284742, 2012). "These types of studies could help elucidate the contribution of TLR2 signaling in the model presented below, in which pathogenic arenavirus fails to create an antiviral environment during the early stages of infection broadly affecting the ability to elicit an efficient adaptive immune response." (PMID 23202459, 2012). "By contrast, TLR2−/− mice suffered more severe disease (reduced weight gain, clinical features), infection and more intense and prolonged inflammation (enhanced NK cell, neutrophil, DC and activated CD8+ T-cell influx and IL-17 responses)." (PMID 22724018, 2012). "The expression level of toll-like receptor 2 (Tlr2) and tumor necrosis factor (Tnf) of A/J mice after infection with SS2 were obviously upregulated." (PMID 22384161, 2012). "The Th2 response in TLR2 knockout mice is significantly elevated compared to wild type mice at 10 weeks p.i., indicating TLR2 interactions suppress Th2 response following aerosol infection." (PMID 22973560, 2012). "We decided to focus on TLR2/4 since these TLRs are activated by RSV in immune cells like macrophages and previous studies have shown that TLR2/4 are involved in IL-1β secretion during infection with other pathogens." (PMID 22295065, 2012). "In our lab we also found that the inoculation of TLR2-synthetic ligand prior to infection in vivo improved the survival of lethally infected mice." (PMID 21869919, 2012). "Among these, TLR2 which recognizes lipotechoic acids and lipopeptides, contributes to the innate response against infection." (PMID 22432012, 2012). "By day 6 post-infection, 90% of the wild type and TLR4−/− mice had succumbed to infection, while over 60% of the TLR2−/− mice survived and half of the survivors were symptom free throughout the study." (PMID 23061052, 2012). "Infection of wild-type, tlr2−/−and trif−/− macrophages with EGDe or ΔpgdA showed that both TLR2 and the adaptor were required for full induction of IκB mRNA in response to EGDe and ΔpgdA strains." (PMID 22432012, 2012). "Clinical features were monitored using a scoring matrix to determine the quantitative clinical effects of the absence TLR2 and 4 during infection." (PMID 22724018, 2012). "However, these responses were not sufficient enough to protect the deficient mice from Mtb infection within 5 months after infection suggesting that TLR-2 might be a regulator of inflammation, and the exaggerated immune inflammatory response in these mice resulting from the absence of TLR-2." (PMID 22570668, 2012). "The infection of human THP1-derived macrophages by L. donovani in vitro suppresses TLR2 and TLR4-stimulated IL-12 release, with an increase in IL-10 production, through parasite-dependent contact." (PMID 22523644, 2012).
infection (continued). "TLR2 signaling also enhances infection of quiescent naïve and memory CD4+ T cells, which are normally relatively resistant to HIV infection." (PMID 22844428, 2012). "The results reveal Th2-skewed immune responses in TLR2−/− mice late in infection and support a TLR2 requirement for efficient clearance of Brucella from the lungs, but not from the spleen or liver." (PMID 22973560, 2012). "TLRs are among the most important PRRs for the recognition of mycobacterial PAMPs during the early stages of infection, particularly the cell surface TLR2 (acting alone or as a heterodimeric complex with TLR1 or TLR6) and TLR4 receptors." (PMID 22384131, 2012). "In a Paracoccidoides brasiliensis intratracheal infection model, TLR2 promotes Treg expansion, thereby limiting Th17 cell differentiation and tissue pathology." (PMID 23189270, 2012). "Female mice were found to have higher levels of cardiac TLR2 mRNA at 3 days post infection (p.i.)compared to males." (PMID 23241283, 2012). "We assessed the effect of triggering TLR2, TLR3, TLR4, and TLR7 with selected ligands on the susceptibility of the J774A.1 macrophage cell line to infection with murine coronavirus (mouse hepatitis virus, [MHV])." (PMID 22754655, 2012). "In a model of chronic fungal asthma, TLR2−/− mice show impaired airway hyper-responsiveness to A. fumigatus and reduced fungal clearance at early infection stages." (PMID 23189270, 2012). "In HSV-1, CD200R1 supports infection at or before the stage of early gene expression, which in turn regulates the surface expression of TLR2." (PMID 23082204, 2012). "TLR2−/− mice had more severe disease and more intense and prolonged infection compared to other groups." (PMID 22724018, 2012). "The resistance to infection with T. cruzi is known to depend on appropriate MyD88 signaling after stimulation of TLR2 and TLR9, and TLR4." (PMID 22348160, 2012). "In summary, in Chlamydia respiratory infection in early life, it is likely that TLR2 responses are induced very early and control infection." (PMID 22724018, 2012). "Signaling through the TLR2 by the parasite-released-antigen Tc52 stimulated the maturation of DCs and strikingly rescued immunized mice from lethal infection." (PMID 21869919, 2012). "Following infection wild-type, TLR2−/− and TRIF−/− mice developed comparable diarrhoea and transient weight loss, which peaked at day 3 post-infection." (PMID 21738466, 2011). "We observed that TLR2−/− mice had significantly reduced Tregs 10 days after infection compared to WT mice." (PMID 21695198, 2011). "The role of TLR2/MyD88 in the differentiation of Lin− cells are in line with several previous reports showing that TLRs have a role in haematopoiesis during infection." (PMID 21935459, 2011). "This is consistent with the results obtained in our study where the enhancement of TLR4 was accompanied of increased number of TLR2 (+) cells previous and post infection." (PMID 21813005, 2011). "Although TLR2-deficient BMDC were impaired to secrete TNF and IL-12p40 upon infection with C. pneumoniae in vitro, both factors were presumably not required for T-cell stimulation." (PMID 22096480, 2011). "During short-term infection, aortic expression of both Tlr2 and Tlr4 was significantly up-regulated." (PMID 21625524, 2011). "By 14 h post-infection, the levels of cell death in wild-type and TLR2−/− macrophages were equivalent (∼96%), demonstrating that TLR2 contributes to rapid inflammasome-dependent cell death but is not absolutely required for this process." (PMID 21698237, 2011). "Because S100B production mainly occurred in infection via the TLR2/MyD88 pathway, our findings indicate the existence of an autocrine/paracrine loop by which TLR2–induced S100B binds to extracellular RAGE to inhibit TLR2 upon physical association." (PMID 21423669, 2011).
infection (continued). "Upon infection of macrophages, F. novicida is initially recognized by TLR2 at the plasma membrane and in the phagosome, leading to the induction of a proinflammatory response dependent upon MyD88 and NF-κB." (PMID 21698237, 2011). "Here, we explored the involvement of TLR-2 and TLR-5 in THP-1 cells and HEK293 cell lines (stably transfected with TLR-2 or TLR-5) during infection with wild-type H. pylori and isogenic cagPAI mutants." (PMID 21573018, 2011). "We therefore analyzed the expression of TLR2 in retinas of wild type mice during the course of infection." (PMID 22163046, 2011). "Further understanding of the mechanisms by which TLR2 and other components of innate immunity respond to B. cereus and other organisms in the eye could facilitate the development of new therapeutic regimens to hamper inflammation and prevent vision loss during this blinding infection." (PMID 22163046, 2011). "Our data agrees with these observations since TLR2 was up-regulated after infection of MAH strains 2.6-fold after 24 h." (PMID 21629653, 2011). "Despite low levels of TLR2 in the mouse brain in basal condition, it is strongly induced in microglia following infection or brain injury." (PMID 21989292, 2011). "In that study, upregulation of TLR2 by Pam3Cys prior to infection led to reduced numbers of intraocular staphylococci and preservation of retinal function, compared to untreated infected control mice." (PMID 22163046, 2011). "TLR2 activation leads to a proinflammatory response that recruits neutrophils, monocytes, T cells, and B cells to the infection site." (PMID 22567325, 2011). "We also observed downregulation of TLR2 (4.3-fold after 4 hours, 3.8-fold after 8 hours, and 1.2-fold after 24 hours of infection)." (PMID 21437210, 2011). "We observed increased levels of active caspase-1 in the livers of wild-type mice compared to TLR2−/− mice 4 h post-infection." (PMID 21698237, 2011). "Studies have reported increased expression of TLR2 in response to infection and inflammation, while others have reported decreased or attenuated expression." (PMID 22163046, 2011). "At 6.5 h post-infection, the supernatants of wild-type macrophages infected with F. novicida contained significantly increased levels of IL-18 compared to infected TLR2−/− macrophages." (PMID 21698237, 2011). "To further test the role of TLR2 in inflammasome-dependent responses, we measured the levels of IL-1β and IL-18 in macrophage supernatants following infection with F. novicida." (PMID 21698237, 2011). "We found that 15% of wild-type macrophages infected with L. monocytogenes at an MOI of 20∶1 underwent cell death at 1 h post-infection, while only 3% of TLR2−/− macrophages died." (PMID 21698237, 2011). "TLR2 recognition of Francisella lipoproteins likely occurs in the phagosome and results in protection of mice from lethal infection." (PMID 22567325, 2011). "In vivo, however, the infection induced the expression of the co-stimulatory molecules CD86 and CD80 as well as MHC class II by CD11c+ cells in wild type and TLR2/4 double-deficient mice with comparable efficiency." (PMID 22096480, 2011). "TLR2 also contributed to inflammasome activation in response to infection by the cytosolic bacterium Listeria monocytogenes." (PMID 21698237, 2011). "It remains to be determined if the exhausted condition of CD8 towards parasite antigens is a cause or a consequence of the progressive infection of DCL patients by Leishmania mexicana and if TLR2 induces downregulation of PD-1 pathway." (PMID 21072232, 2010). "We found that TLR2 was 6-fold up-regulated 24 h after infection solely in infected quarters and accordingly TLR4 2-fold." (PMID 20184744, 2010). "We analyzed the induction of IFN-γ and cytotoxic activity in vivo in TLR2-, TLR4-, TLR9- or MyD88-deficient mice during infection, and found intact responses compared to WT mice." (PMID 20442858, 2010).
infection (continued). "There are clearly additional TLR2-independent mechanisms in the lung, perhaps initiated by cell damage due to higher numbers of organisms, contributing to host responses to infection." (PMID 20505832, 2010). "The same was observed upon infection by MHV-68 highlighting the importance of the TLR2-MyD88 pathway for IL-6 secretion in response to the virus." (PMID 21060793, 2010). "Based on our in vitro studies, we predicted that cytokine production would be reduced in infected mice; however, TLR2−/− mice had higher levels of cytokines in BAL fluids 72 hours after infection, corresponding to the higher numbers of M. pulmonis in the lung." (PMID 20505832, 2010). "Increased viral load observed in TLR2−/− mice after 5 days of infection indicates that TLR2 has a protective role in early defense against MHV-68 infection." (PMID 21060793, 2010). "Four hours after infection with 105 LSE, TLR2-deficient macrophages also demonstrated diminished production of IL-6, as well as the chemokines CXCL1 and CXCL2." (PMID 20404927, 2010). "It has been shown that infection with viruses such as influenza A virus can induce an upregulation in TLR2 expression by human neutrophils." (PMID 21060793, 2010). "TNF-alpha, IL-6 and IL-10 expression was also modulated upon infection showing a TLR2-specific dependent IL-10 secretion." (PMID 20523725, 2010). "In fact, previous studies indicate that modulation of TLR2 expression on respiratory epithelium can alter mucin production in response to infection with the human pathogen, M. pneumoniae." (PMID 20505832, 2010). "Using an innate immune-mediated IBD model triggered by infection with H. hepaticus we found that 129RAG−/−.TLR2−/− mice developed bacterially driven typhlocolitis comparable to that of TLR2-competent controls." (PMID 19950179, 2010). "Purified WT or TLR2−/− NK cells were co-cultured in vitro with WT or TLR2−/− CD11c+ DCs, followed by infection with VV." (PMID 20300608, 2010). "TLR2-dependent IL-6 production was detected as early as 6 hours post-infection and was sustained at 18 and 24 hours." (PMID 21060793, 2010). "That preferentially TLR2 is up-regulated in line with the observation that in our patients infection with Gram-positive bacteria is prevalent." (PMID 21151520, 2010). "In humans 3 β defensins (HBD1, HBD2, and HBD3) are expressed; HBD2 has been shown to be upregulated upon infection and can also be induced upon TLR2 activation and chemotactically attract neutrophil to the site of infection." (PMID 23282714, 2010). "At day 5 post-infection, both MyD88−/− and TLR2−/− mice had reduced lung IL-6 concentrations when compared to WT mice." (PMID 21060793, 2010). "Immune response-associated genes, with altered expression in virulent strain infection, were selected for further investigation: Tlr2, Tlr4, Tlr13, Myd88, Il1b, Il6, dectin-2 and Cxcl12." (PMID 19845042, 2009). "TLR2−/− and MyD88−/− mice also showed increased bacterial burdens in lungs, liver, and spleen compared to controls following i.n. infection." (PMID 19936231, 2009). "The reduced survival time for the MyD88−/− mice also correlated with a greater increase in bacterial burden compared to TLR2−/− mice beginning on day 3 post-infection." (PMID 19936231, 2009). "Effect sizes of louse infection grade on the most intense responses (TLR2 and TLR9) and on total TNF-α (summed over all receptor-ligand combinations), TIR, were striking." (PMID 19386086, 2009). "In response to P. aeruginosa, genes associated with IFN-γ response to infection (CXCL10, IL-24, IFNγR2) and other mediators of anti-infectious responses (CSF2, MMP1, MMP3, TLR2, S100 calcium-binding proteins A) were markedly up-regulated in wild-type TG cells." (PMID 19399182, 2009). "In an attempt to shed light on the exact mechanism(s) by which TLR2 triggering can increase HIV-1 productive infection of IM-MDDCs, we performed viral entry assays." (PMID 19419540, 2009).